MDM2 (MDM2 proto-oncogene)
Diseases named in the same sentence as MDM2 in open-access papers (continued):
Sharing a sentence is not in itself a finding about the gene and the disease.
tumor (continued). "Tumors treated with the MDM2 inhibitor AMG-232 showed enhanced anti-tumor effects mediated by T cells, concomitant with reduced IL-6 secretion." (PMID 39263534, 2024). "Our previous high-throughput screening results indicated that depletion of ULK1 significantly increased the sensitivity of tumor cells to MDM2 inhibitors and induced classical pyroptosis in these cells." (PMID 39215364, 2024). "The histopathological findings of our patient’s surgical specimen showed the proliferation of mature and variously sized adipocytes and ectopic ossification, and the immunohistochemical staining indicated that tumor nuclei were positive for MDM2 and CDK4." (PMID 39109289, 2024). "Murine double minute 2 (MDM2), an E3 ubiquitin ligase, is highly expressed in ovarian clear carcinoma cells, and MDM2 was found to inhibit T cell-mediated tumor killing induced by ICB; AMG232 is a selective MDM2 inhibitor." (PMID 39253578, 2024). "The mouse double minute 2 (MDM2) fluorescence in situ hybridization (FISH) assay was positive for tumor cells, that is, MDM2 gene amplification." (PMID 38287440, 2024). "In RPL-DDLPS, extracellular vesicles carrying “cargo” MDM2 are released into the microenvironment, and MDM2 DNA from RPLPS is transferred to target recipient cells—preadipocytes—in the tumor microenvironment." (PMID 39723387, 2024). "This study showed that high MDM2-expressing tumor cells have increased affinity for T cells and directly kill MDM2-overexpressing cancer cells." (PMID 39263534, 2024). "Despite peptide-specific killing, these low-avidity CTLs were insufficient in inducing lysis of human tumor cells that expressed MDM2." (PMID 38281981, 2024). "Immunohistochemistry analysis revealed a positive reaction for MDM2 and a Ki67 proliferation marker of 20% to 80% in tumour cells." (PMID 38732333, 2024). "Analysis of this patient’s tumor showed high levels of amplification of MDM2 and CDK4 likely indicating that despite the unique morphological features, bone formation shared many of the cytogenetic features of the common forms of DDL." (PMID 39687824, 2024). "Tumor regression has been achieved in both in vitro experiments and in the MDM2-amplified SJSA-1 osteosarcoma model." (PMID 39684639, 2024).
tumor (continued). "We found that in vitro, the small molecule MDM2 inhibitors Siremadlin and Navtemadlin inhibited tumor cell growth at lower concentrations than the stapled peptide Sulanemadlin." (PMID 38784022, 2024). "We report a synergistic tumor reducing effect when the MDM2/MDMX inhibitor Sulanemadlin is combined with anti-PD-1 therapy with the monoclonal antibody DX400." (PMID 38784022, 2024). "Antigen-specific CD8 + autologous T lymphocytes can identify MDM2, and its epitopes can serve as a TAA to activate cytotoxic T lymphocytes (CTLs) that can eliminate tumor cells expressing MDM2." (PMID 38281981, 2024). "Preclinical experiments with MDM2 inhibitors have shown paradoxical results because they can enhance anti-tumor effects by promoting T lymphocyte proliferation and M1 macrophage polarization, which are inhibited by promoting immune checkpoint expression." (PMID 39263534, 2024). "We also showed that this negative regulation of DICER by USP7 via MDM2 was relevant to human tumours using cellular and clinical data." (PMID 37867415, 2024). "SUMOylation can modulate tumor-suppressing and tumor-promoting genes, such as the enhanced function of the oncogenic protein MDM2 upon SUMOylation, which promotes cell proliferation and survival, driving tumor progression." (PMID 39723246, 2024). "Our relative expression analysis demonstrated that tumor tissues presented significant higher expression levels of MDM2-FL and MDM2-ALT2 in comparison to NAT." (PMID 39769278, 2024). "Preclinical and clinical studies of MDM2 inhibitors have supported the viability of this approach to mediate anti-tumor activity." (PMID 39144622, 2024). "The proportion of tumour samples exhibiting MDM2 amplification ranged from 3.4 to 10.0% for BTC overall." (PMID 39302603, 2024). "Although most preclinical experiments with MDM2 inhibition have demonstrated tumor suppression, the impact of PD-L1 up-regulation should be determined in further clinical trials." (PMID 39263534, 2024). "It has been reported that the combined use of BCL2, CDK4/6 inhibitors or MEK inhibitors can synergistically enhance the anti-tumor effects of MDM2 inhibitors in different types of tumors." (PMID 39215364, 2024). "Characterized by a low tumor mutation burden and frequent chromosomal structural abnormalities, DDLPS often exhibits amplification of the MDM2 gene." (PMID 39048965, 2024).
tumor (continued). "In approximately 90% of DDLPS cases, FRS2 is coamplified with MDM2 and plays a role in tumor progression." (PMID 39723387, 2024). "This literature review found that the proportion of tumours exhibiting MDM2 amplification ranged from 3.4 to 10.0% for BTC overall." (PMID 39302603, 2024). "In the Phase Ib trial in patients with advanced WDLPS or DDLPS, combining an MDM2 inhibitor with a CDK4/6 inhibitor ribociclib was demonstrated to have an initial anti-tumor effect and a controlled safety profile." (PMID 39606156, 2024). "This review provides a synthesis of evidence on the epidemiology of BTC and the frequency of MDM2 amplification in BTC tumours." (PMID 39302603, 2024). "MDM2 amplification prominently destructs FBW7 tumor suppressor and stabilize MCL-1 anti-apoptotic protein to evade apoptotic cell death." (PMID 39543744, 2024). "Tumor cells play an important role in the regulation of tumor immune escape through the regulation of MDM2." (PMID 39263534, 2024). "Immunohistochemical staining indicated that the tumor cells were positive for murine double minute 2 (MDM2) and cyclin-dependent kinase 4 (CDK4), and negative for pleomorphic adenoma gene 1 (PLAG1)." (PMID 39109289, 2024). "PDTOs developed from both WD and DD LPS human samples were assessed for MDM2 amplification to ensure that the outgrowth of tumor cells was maintained." (PMID 39272889, 2024). "At the end of experiment, the average size and weight of xenograft tumor in PC-9 MDM2 group was 12-fold and 5-fold than that in PC-9 NC group, respectively." (PMID 39543744, 2024). "Our analysis using the TCGA public database revealed that MDM2 is highly expressed in most tumor tissues and that its expression is negatively correlated with patient prognosis." (PMID 39215364, 2024).
tumor (continued). "Second, a multitude of downstream substrates of Akt, including FoxO, mTOR, MDM2, and NF-κB, influence the survival, proliferation, and metabolism of tumor cells through their downstream effectors, ultimately determining cell fate." (PMID 39537605, 2024). "Despite the promising anti-tumor effects of MDM2 inhibitors in preclinical studies, their efficacy in clinical studies is unsatisfactory, and adverse effects limit their further application in the clinic." (PMID 39263534, 2024). "For instance, dual-target inhibitors targeting MDM4/MDMX and XIAP have shown good tumor inhibition potential and avoidance of MDM2 feedback activation in both in vitro and in vivo models." (PMID 39215364, 2024). "Here, we observed a significant association between a shortened EFS of abemaciclib-treated patients with metastasized luminal BC and increased mdm2 gene copy numbers in tumor cells, even though the analyzed cohort is small yet." (PMID 39000582, 2024). "Their results showed that miR-194, a regulator of the MAP4K4/c-Jun/MDM2 signaling pathway, can act as a tumor suppressor and introduced it as a new target for the prevention and treatment of CRC44." (PMID 36854781, 2023). "The tumor showed EGFR C797S, T790M, exon 19 deletion (T751_I759>N), CDK4 amplification, MDM2 amplification, CDKN2A/B loss, MTAP loss, low MSI, low TMB and negative PD-L1." (PMID 38111812, 2023). "In the cases of invasive BC from the TCGA database in UALCAN, the mRNA levels of AKT1, ESR1, HSP90AA1, CASP3, SRC, and MDM2 were significantly increased in tumor tissues." (PMID 36882618, 2023). "NMD inhibition has also been shown to inhibit tumor growth in an MDM2-overexpression xenograft tumor model." (PMID 36979640, 2023). "In the present study, we aimed to validate gene amplification, protein expression, and the putative tumor biological function of MDM2 in a well-characterized Western GC cohort." (PMID 37821635, 2023). "The models showed characteristic copy number variations (CNV) of disease-related genes (e.g., MDM4, EGFR, CDKN2A, CDK4, and MDM2) that were fairly consistent with the primary tumor." (PMID 37508520, 2023). "MDM2 is an E3 ligase, which can carry out ubiquitination reactions against various substrates, and has a positive effect on the proliferation of tumor cells." (PMID 37959819, 2023).
tumor (continued). "In tumor tissues, seven gene amplification mutations included CDK4 (Mutation abundance, MA:1.57), AKT2 (MA:1.65), CCND2 (MA:1.63), MDM2 (MA:1.57), NTRK1 (MA:2.38), AXL (MA:1.65), and KRAS (MA:1.63), as well as the AFF3 gene missense (c.1781_1787del insC)." (PMID 37089080, 2023). "AMG-232 inhibition of MDM2 lowers the expression of IL-6 which consequently sensitizes MDM2 upregulated tumor cells to T cell-mediated death." (PMID 37314603, 2023). "Epithelial cells with a sustained increase in MDM2 expression overpower the tumor inhibitory role of TGF-β and allow transition from epithelial to mesenchymal cells through re-regulating Snail, vimentin, E-cadherin, and N-cadherin." (PMID 37314603, 2023). "The newer generation of MDM2 inhibitors has shown improved specificity and likely better activities in tumor inhibition." (PMID 37298520, 2023). "The patients with high MDM2 were younger and had more invasive behavior, larger tumor volumes and shorter recurrence times compared with patients with low MDM2." (PMID 36837574, 2023). "We also found amplifications of CDK4 and MDM2 with PDGFRA gain in the recurrent tumor and upregulated protein expressions of these genes." (PMID 38012788, 2023). "In contrast, the MDM2 protein was consistently detected in basal and parabasal cells of morphologically normal epithelium outside of the invasively developing tumor." (PMID 37081989, 2023). "The synthetic lethal effect of the MDM2 inhibitor was further validated in mice tumor xenograft models of PTEN-isogenic CRC." (PMID 37496993, 2023). "This study proposes a novel and important function of S100A6 in regulating MDM2 that directly affects the growth of tumor cells and their sensitivity to chemotherapy, which is of high value in clinical use." (PMID 37217945, 2023). "MDM2 amplification is a common finding in malignant soft tissue tumors and infrequent in other tumor types." (PMID 37821635, 2023). "Momand and colleagues demonstrated that, among 4000 tumor samples of 28 different cancer types, an enhanced amplification of the MDM2 gene occurred in 7% of human cancers." (PMID 36770991, 2023).